BRAF (B-Raf proto-oncogene, serine/threonine kinase)
Diseases named in the same sentence as BRAF in open-access papers (continued):
Sharing a sentence is not in itself a finding about the gene and the disease.
melanoma (continued). "But also in BRAF V600 wild-type melanoma immunotherapy might be preferred compared to (poly-)chemotherapy as a first line treatment in patients with both markers within the normal range." (PMID 24312329, 2013). "In fact, it is not completely elucidated how BRAF or NRAS mutations contribute to the emergence of benign melanocytic nevi as they are also the most frequent mutated genes in melanoma, occurring in early stages of tumor progression." (PMID 24222856, 2013). "SNVs were considered if detected in both malignant melanoma (BRAF mutant) samples." (PMID 23922754, 2013). "In addition to increasing pro-oxidative stress, HSP90 inhibition or ER stress inducers have been also shown to be valuable therapeutic targets in BRAF mutant melanoma enabling to overcome acquired resistance to vemurafenib." (PMID 24161908, 2013). "However, another study revealed that BRAF-mutant melanoma cells are resistant to metformin in vitro, while metformin accelerates their growth in vivo." (PMID 23875169, 2013). "Furthermore, recent and ongoing clinical trials show clinical activity of BRAF inhibitors in patients with asymptomatic melanoma brain metastases." (PMID 24133630, 2013). "The first one is vemurafenib, a selective inhibitor of BRAF-activating mutations which are found in more than 50% of melanomas and which cause constitutive activation of the MAPK/ERK pathway driving uncontrolled melanoma growth." (PMID 23890105, 2013). "BRAF or NRAS mutated nevi did not have a higher chance to be associated with melanomas than wild type nevi." (PMID 23861977, 2013). "In contrast, BRAF mutations were recorded in 16 out of 41 melanomas without BRAF gains, revealing a statistically significant association between BRAF copy-number gains and V600 mutation status (p = 0.047)." (PMID 23673558, 2013). "In 2012, 4,629 tests for BRAF p.V600 were performed in France, in patients with melanomas." (PMID 24119386, 2013). "Therefore, cotargeting HDACs and mutant BRAF can bypass canonical cell death pathways to kill BRAFV600E melanoma cells." (PMID 23744355, 2013). "Phosphorylated STAT3 transcriptionally activates PAX3 expression in melanocytes, and the silencing of STAT3 or PAX3 using RNAi was recently shown to inhibit the growth of melanoma cells, particularly in melanoma cells that have acquired resistance to the BRAF inhibitor, vemurafenib." (PMID 24062982, 2013). "Cooccurrence of BRAF and PTEN mutations was reported in 17% of melanomas." (PMID 24416617, 2013). "BRAF inhibitors (BRAFi) have revolutionized the treatment of melanoma." (PMID 24192036, 2013). "One patient had a BRAF mutation in the primary melanoma and not in the two metastatic sites (bone and liver); three patients had a BRAF mutation in the metastatic tumors and not in primary tumors." (PMID 23976959, 2013). "In addition, the results reveal that coadministration of the HDAC inhibitor SAHA and the BRAF inhibitor vemurafenib inhibits melanoma xenograft growth independently of caspases in vivo." (PMID 23744355, 2013). "The major finding of our study is that in contrast to current belief, neither morphology nor the presence of BRAF or NRAS mutation predicts the chance of malignant transformation of a nevus into a melanoma." (PMID 23861977, 2013). "Inhibition of this pathway may be a suitable strategy for enhancing and/or prolonging the antitumor effects of BRAF inhibitors or other anticancer agents in melanoma brain metastases." (PMID 24133630, 2013). "Vemurafenib, an inhibitor of BRAF V600E mutant, has been approved for advanced melanoma therapy." (PMID 24252729, 2013). "In light of the fact that BRAF status in melanoma is a predictor of response to BRAF inhibitors, it would also be important to examine the expression and localization of PRMT5 in BRAF inhibitor-resistant versus inhibitor-sensitive cells, or in tumors which are or are not responsive to immunotherapy." (PMID 24098663, 2013).
melanoma (continued). "Trying to generalize miR-126&126* function, as recipients of miR transduction we selected two metastatic melanoma cell lines characterized by a different mutational status of BRAF and NRAS (i.e. BRAF V600E and NRAS wt for A375M and BRAF wt and NRAS Q61R for Me665/1)." (PMID 23437250, 2013). "In this single institution study, we correlated mutation status and expression levels of BRAF and NRAS to dacarbazine (DTIC) treatment response as well as progression-free and overall survival in a cohort of 85 patients diagnosed with advanced melanoma." (PMID 23673558, 2013). "The relative contribution of these two mechanisms might determine whether melanoma stem-like cells of wild type BRAF tumors are killed or spared by the treatment." (PMID 24238212, 2013). "However, it is clear that an active cross-talk between these two pathways supports the development of melanoma and leads to resistance to BRAF inhibitors." (PMID 23515890, 2013). "Treatment of advanced melanoma has been improved with the advent of the BRAF inhibitors." (PMID 23890105, 2013). "The 40 kinase substrate signature obtained between BRAF wild-type and BRAF(V600E) melanoma tumor samples after ex-vivo treatment with vemurafenib was similar to the signature obtained with in-vitro vemurafenib treatment between BRAF wild-type and vemurafenib-resistant BRAF(V600E) cells." (PMID 24023633, 2013). "Numerous studies have shown the BRAF mutation does not affect the Disease Free Interval (DFI) or OS after surgical resection of melanomas at these stages (14, –16), and thus it does not influence tumor recurrence." (PMID 23951556, 2013). "However, repeated experience has shown that melanomas acquired resistance even to new agents selectively targeting BRAF." (PMID 23527225, 2013). "Upregulation of gp100 and MART-1 was seen in both BRAF mutant and WT melanoma cell lines." (PMID 24194739, 2013). "Moreover, MEK inhibition with U0126 and knockdown of mutant BRAF resulted in reduced expression of CD200 mRNA in melanoma cell lines." (PMID 24194739, 2013). "Thus, inhibition of PI3K-AKT signaling shows potential for enhancing and/or prolonging the antitumor effect of BRAF inhibitors or other anticancer agents in melanoma brain metastases." (PMID 24133630, 2013). "Since BRAF and NRAS mutations were found to be mutually exclusive (further confirming previous data), a high prevalence of such alterations was observed in our series, with about two thirds of melanomas presenting a BRAF/NRAS mutation." (PMID 23987572, 2013). "It was discovered recently, that melanomas show heterogeneity in regard to BRAF-genotype." (PMID 23861977, 2013). "Although resistance to BRAF inhibition is a challenge, recent evidence suggests that combinational therapy with inhibitors of the MAPK and PI3K pathway may be efficacious in melanoma patients with (V600E) mutations." (PMID 24023633, 2013). "In contrast, BRAF mutation does not appear to have significant impact on prognosis in stage I or stage II melanomas." (PMID 23951556, 2013). "Inhibition of the MAPK pathway in BRAF mutant melanoma leads to increased expression of MDAs (gp100, Mart-1, Tyrp-1, and Tyrp-2), resulting in improved antigen-specific recognition by gp100 and MART-1 specific TCR-transgenic CTL as measured by increased IFN-γ production in vitro." (PMID 24194739, 2013). "Our detection of BRAF mutations in 41 % of patients with cutaneous primary melanomas but lack of mutations among uveal- and mucosa-derived tumors are in accordance with findings by others." (PMID 23673558, 2013). "Less frequent activating BRAF mutations (e.g. V600K, V600D, V600M) have been observed in malignant melanoma and other non-CNS tumors but only rarely have been identified in primary CNS tumors." (PMID 24252190, 2013).
melanoma (continued). "Treatment of melanoma cells with BRAF (V600E)-specific shRNA or MEK inhibitors resulted in decreased immunosuppressive activity of melanoma cells on DCs, suggesting that MAPK signaling pathway in cancer is associated with impaired DC function in melanoma patients." (PMID 23755373, 2013). "Over the last 4 years, the advent of targeted therapy for BRAF mutated melanoma and immune checkpoint inhibitors, e.g. anti-CTLA-4, anti-PD-1, and anti-PD-1 L antibodies have sparked resurgence of excitement for the treatment of advanced stage melanoma." (PMID 24499550, 2013). "However, in BRAFV600E-expressing melanoma cells, the effect of blocking BRAF activity alone clearly dominates, because these cells are exquisitely dependent upon BRAF activity." (PMID 24192036, 2013). "We also found that all of the NRAS mutated melanoma lines evaluated (or included in our panel) had low expression of CDK2, whereas there was some variability within the BRAF-V600E mutated group, with some cell lines harboring high expression of CDK2 and some with low expression." (PMID 23527225, 2013). "This lesion was probably a second melanoma, with a different BRAF status." (PMID 23976959, 2013). "BRAF status according to histological subtype of the primary melanoma site." (PMID 23976959, 2013). "With the exception of the age at diagnosis, the frequency of BRAF mutations was not correlated with any clinicopathological parameters in primary melanomas." (PMID 23987572, 2013). "BRAF V600E mutant melanomas initially have a good response rate." (PMID 24298448, 2013). "Due to the heterogeneous genotypic profile in human melanoma, there was no clear relationship between BRAF or NRAS that predicted effects of PRMT5 loss on proliferation." (PMID 24098663, 2013). "Similarly, oncogenic rearrangements of the RAF kinases, RAF1 and BRAF, have been found in various cancers including pilocytic astrocytoma, melanoma, gastric cancer, and prostate cancer." (PMID 23637631, 2013). "In addition, we demonstrate that SAHA and the clinically available BRAF inhibitor vemurafenib cooperatively inhibit BRAFV600E melanoma xenograft growth in a mouse model." (PMID 23744355, 2013). "Moreover, HGF was also found to induce resistance to sunitinib, ATE684 (a selective ALK inhibitor), vemurafenib (the BRAF inhibitor, in BRAF-mutant melanoma), and lapatinib (a dual HER2 and EGFR tyrosine kinase inhibitor)." (PMID 23533466, 2013). "Mutations in BRAF were significantly more common in melanomas located in areas without chronic sun-induced damage." (PMID 24416617, 2013). "Notably, RAS and BRAF mutations predict sensitivity to MEK inhibition, and patients with melanoma harboring V600EBRAF show comparable results with respect to tumor regression when treated with trametinib and vemurafenib." (PMID 23603840, 2013). "In the remaining discrepant cases, we surprisingly observed a mutated primary tumor and a wild-type metastasis (93% BRAF and 7% NRAS) or, to a less extent, a different mutation pattern between melanoma lesions (NRAS mutation in primary and BRAF mutation in secondary tumors)." (PMID 23987572, 2013). "Among the investigated melanoma cell lines, three display constitutive activation of the Ras/Raf/MEK/ERK pathway through activating V600E BRAF mutation or NRAS mutations: Colo-679 (BRAF V600E mut; Nras wt), IGR-39 (BRAF V600E mut; Nras wt), IPC298 (Braf wt; Nras Q61K mut)." (PMID 22563505, 2012). "Furthermore, c-Met amplification is a primary resistance mechanism to the BRAF inhibitor PLX4032 in patient derived melanoma cell lines." (PMID 22745804, 2012). "Interestingly, BRAF has also been shown to be involved in the progression of melanoma toward metastasis by enhancing its migration." (PMID 23056577, 2012). "BRAF inhibitors have been shown to be effective in the treatment of melanomas." (PMID 23455493, 2012).
melanoma (continued). "Interestingly, combined BRAF (GSK2118436) and MEK (GSK1120212) inhibition was recently shown to overcome NRAS-mediated resistance to BRAF inhibition in melanoma cells already harbouring BRAFV600 mutations." (PMID 23039341, 2012). "In melanoma cells RAS mutations are not equivalent to BRAF mutations since they activate the MAPK pathway in different ways." (PMID 22339359, 2012). "Many malignant melanoma cells become addicted to mutant BRAF for proliferation." (PMID 23006971, 2012). "Therefore, in current neuropathological practice BRAF testing is of clinical importance in tissue samples of melanoma brain metastases in order to identify cases amenable to therapy with BRAF inhibitors." (PMID 22385786, 2012). "Recently, the results of a phase II clinical trial (NCT00949702) indicated that vemurafenib induces clinical responses in greater than 50% of previously treated mutant BRAF (V600E or V600K) melanoma patients the median overall survival was approximately 16 months." (PMID 23085539, 2012). "However, BRAF V600E expression in a PTEN gene-silenced background led to the production of melanomas with 100% establishment, short latency and metastasis to lymph nodes and lungs." (PMID 23006971, 2012). "Two BRAF-mutant melanoma patients responded and one NRAS- mutant melanoma patient responded." (PMID 23085539, 2012). "Melanoma cells constitutively harbor - besides well-defined mutations in certain proto-oncogenes like BRAF and NRAS - also non-random genomic alterations reflecting chromosomal instability (CIN)." (PMID 22535842, 2012). "Vemurafenib was approved for the treatment of unresectable metastatic BRAF mutant melanoma in 2011." (PMID 23085539, 2012). "The dual PI3K/mTOR inhibitor NVP-BEZ235 inhibited melanoma growth regardless of BRAF mutation status." (PMID 23455493, 2012). "BRAF-mutant melanoma cells are normally very sensitive to AZ628." (PMID 23085539, 2012). "However, recent clinical trials using a BRAF inhibitor revealed encouraging results for patients with advanced BRAF mutant bearing melanoma, but drug resistance accompanied by recovery of phospho-ERK (pERK) activity present challenges for this approach." (PMID 22277029, 2012). "In the NCI-60 panel, there are 11 BRAF mutant cell-lines, including all eight melanoma lines." (PMID 23209617, 2012). "In comparison to other targeted agents such v-raf murine sarcoma viral oncogene homolog B1 (BRAF) inhibitors in melanoma or crizotinib in anaplastic lymphoma receptor tyrosine kinase (ALK) translocated tumors, the number of objective responses to PI3K inhibitors is less dramatic." (PMID 23232172, 2012). "To demonstrate that BRAFV600E is also sufficient to suppress AKT pathway activation in melanoma cells, we transiently expressed BRAFV600E or wild-type BRAF in CHL1 melanoma cells that contain endogenous wild-type BRAF and assessed the induction of pAKT in response to MEK inhibitor treatment." (PMID 22880048, 2012). "In summary, at this point BRAF V600E testing is clinically indicated in relatively few cases of the daily clinical neuropathology practice, but has important predictive implications for patients with melanoma brain metastases." (PMID 22385786, 2012). "We report here development, validation, and implementation of an assay designed to simultaneously detect 43 common somatic point mutations in 6 genes (BRAF, NRAS, KIT, GNAQ, GNA11, and CTNNB1) potentially relevant to existing and emerging targeted therapies specifically in melanoma." (PMID 22536370, 2012). "The MEK inhibitors may be appropriate for the treatment of certain melanomas which have mutant BRAF." (PMID 23085539, 2012). "That contrasts with positive results in renal cell carcinoma and suggests that melanoma could be specifically more dependent of the BRAF pathway." (PMID 22216021, 2012). "In addition to BRAF inhibitors, patients are directed to trials for KIT mutations, GNAQ/11 mutations in uveal melanoma, and even NRAS mutant melanoma." (PMID 22536370, 2012).
melanoma (continued). "Using an NIH3T3 stable cell line expressing BRAFV600E and various melanoma cell lines (BRAF WT or V600E), we demonstrated that BRAFV600E not only suppresses MEK inhibitor or rapamycin-induced AKT pathway activation but also negatively regulates basal AKT pathway signaling." (PMID 22880048, 2012). "Because of the extensive clinical, histologic, and immunohistochemical similarities with melanoma, we decided to analyze whether CCS also has mutations in the BRAF and NRAS gene." (PMID 22693489, 2012). "Furthermore, this drug combination was recently shown to induce tumour regression or stable disease in roughly two-thirds of BRAFV600 mutant melanoma patients refractory to single-agent BRAF inhibition." (PMID 23039341, 2012). "Such signal transduction-mediated resistance is not limited to melanoma since it was recently found that BRAF-mutant colorectal carcinomas might subvert BRAF inhibitor monotherapy through a feedback loop involving activation of EGFR." (PMID 23285177, 2012). "However, short period of symptom free survival and resistance to drug therapy are new emerging problems in BRAF specific inhibitor treatments in melanoma patients." (PMID 23056577, 2012). "Based on the heterogeneity of melanoma cells, secondary resistance may be attributable to BRAF heterogeneity." (PMID 22281663, 2012). "Overall, the alterations in major components of the MAPK, such as BRAF and NRAS mutations, and mTOR pathways, PTEN loss and AKT overexpression, seem to have substantial influence in melanoma progression, being both pathways linked to survival and chemoresistence in melanoma." (PMID 22408430, 2012). "In BRAF mutant cells, loss of PTEN function plays an important role in the development of melanoma in mouse models, as BRAF mutations alone do not induce melanoma but melanoma develops when PTEN is deleted in melanocytes which harbour the BRAF mutation." (PMID 22475322, 2012). "This suggests that melanoma cells are unlikely to change their BRAF mutational status during the formation of brain metastasis." (PMID 22594466, 2012). "When rictor was immunoprecipitated in A375 melanoma cells, BRAF was detected in the rictor complex, in addition to mTOR and sin1 (core components of mTORC2), but not raptor (a component of mTORC1), suggesting that BRAFV600E may interact with mTORC2 directly." (PMID 22880048, 2012). "Loss of PTEN and RAS activation seems comparable in their ability to increase oncogenic signalling through PI3K pathway, due to the coexistence of PTEN somatic mutations in melanoma harbouring BRAF mutations but not with NRAS." (PMID 22408430, 2012). "The co-existence of BRAFmutant and NRASmutant tumor cells has potential clinical implications as in-vitro studies have demonstrated that pharmacologic inhibition of wild-type BRAF in the presence of oncogenic RAS can promote melanoma proliferation and/or resistance to apoptosis." (PMID 22235286, 2012). "Furthermore, a Phase I clinical trial with a potent inhibitor of BRafV600E kinase demonstrates that BRaf-mutant melanomas are highly dependent on BRaf kinase activity." (PMID 22611400, 2012). "We assess whether treatment with BRAF inhibitors in melanoma patients should be interrupted as soon as disease progression appears or continued beyond progression, through the administration of additional compounds." (PMID 22594466, 2012). "This high number of differentially expressed microRNAs may be because eight of the 11 BRAF mutant cell-lines are melanoma cell-lines." (PMID 23209617, 2012).